TAAR5 (trace amine associated receptor 5)
Description:
Olfactory receptor specific for trimethylamine, a trace amine. Also activated at lower level by dimethylethylamine. Trimethylamine is a bacterial metabolite found in some animal odors, and to humans it is a repulsive odor associated with bad breath and spoiled food. Trimethylamine-binding causes a conformation change that triggers signaling via G(s)-class of G alpha proteins (GNAL or GNAS).
Synonyms: TaR-5; PNR
Tractability: Small molecule: it belongs to a druggable protein family. Antibody: UniProt places it where antibodies can reach, with high confidence; its Gene Ontology location is reachable by antibodies, with high confidence; UniProt predicts a signal peptide or a membrane-spanning region. PROTAC: a small molecule that binds it is known.
Target class: Family A G protein-coupled receptor; Membrane receptor
Gene: Protein-coding gene on chromosome 6 (132,588,592 to 132,589,741, reverse strand). Ensembl gene ENSG00000135569.
Subcellular location: Cell membrane
Pathways (Reactome):
Signal Transduction: Amine ligand-binding receptors; G alpha (s) signalling events
Gene Ontology:
Molecular function: trimethylamine receptor activity; G protein-coupled receptor activity; trace-amine receptor activity
Biological process: adenylate cyclase-activating G protein-coupled receptor signaling pathway; cognition; G protein-coupled receptor signaling pathway; sensory perception of smell; signal transduction; sensory perception of chemical stimulus
Cellular component: plasma membrane; membrane
Genetic constraint (gnomAD): Loss-of-function variants: 27 observed, 21.95 expected, observed/expected ratio (o/e) 1.23, 90% interval 0.9 to 1.68. The upper end of that interval is the gene's LOEUF score, 1.68, which puts it in group 6 of 6, group 1 being the genes least tolerant of losing a copy. Missense variants: 495 observed, 424.71 expected, observed/expected ratio (o/e) 1.17, 90% interval 1.08 to 1.25. Synonymous variants: 203 observed, 176.43 expected, observed/expected ratio (o/e) 1.15, 90% interval 1.02 to 1.29.
Homologues: Orthologues: chimpanzee TAAR5 (99% identical), macaque TAAR5 (98% identical), rabbit TAAR5 (88% identical), dog TAAR5 (88% identical), mouse Taar5 (87% identical), rat Taar5 (85% identical), guinea pig TAAR5 (84% identical), zebrafish taar13c (43% identical), zebrafish taar13b (42% identical), zebrafish taar13a (42% identical), zebrafish taar13d (42% identical), zebrafish taar13e (41% identical). Paralogues in human: TAAR9 (44% identical), TAAR8 (43% identical), TAAR6 (42% identical), TAAR2 (40% identical), TAAR1 (39% identical), HRH2 (29% identical), HTR4 (27% identical), DRD4 (27% identical), HTR1D (27% identical), HTR1A (26% identical), DRD5 (26% identical), DRD3 (26% identical), and 13 more.
Diseases named in the same sentence as TAAR5 in open-access papers:
TAAR5 is named in the same sentence as 29 diseases in open-access papers, as found by Europe PMC text mining. Sharing a sentence is not in itself a finding about the gene and the disease. The quoted sentences say what the papers report.
Anxiety (9 papers, 2020 to 2025). Intense feelings of nervousness, tension, or panic often arise in response to interpersonal stresses. "Collectively, the impact of Taar5 deficiency on cognitive, depression, and anxiety-like behaviors was very modest." (PMID 41278968, 2025). "Since the TAAR5 knockout effects, among others, are associated with the decline of anxiety-like and depressive-like behavior in mice, it is considered a prospective target for neuropsychiatric disorders pharmacotherapy." (PMID 39594659, 2024). "Previous behavioral studies indicated a reduction in anxiety-like behaviors in TAAR5-KO mice compared to wild-type controls." (PMID 41511323, 2025). "Future studies are needed to develop potential TAAR5 antagonists for anxiety treatment and to further explore the neural mechanisms through which TAAR5 regulates anxiety." (PMID 40351432, 2025). "Recent studies indicated a connection between trace amine-associated receptor 5 (TAAR5) and emotional behaviors related to anxiety and depression; however, the neurobiological basis of this link is still unclear." (PMID 41511323, 2025). "The predator stress altered the anxiety-related behavior observed in the EPM test for both TAAR5-KO and WT mice." (PMID 41511323, 2025). "The ameliorative effect of TAAR5 gene knockout on depressive-like and anxiety-like behavior allows us to consider its inhibition as the approach to the treatment of neuropsychiatric disorders." (PMID 39594659, 2024). "Behavioral tests have demonstrated that TAAR5 gene knockout in mice (TAAR-KO) leads to reduced anxiety and depression-like behaviors in several tests, as well as increased exploratory behavior in open-field experiments." (PMID 39594659, 2024). "TAAR5 knockout (TAAR5-KO) mice showed alterations in emotional behavior, decreased anxiety, and depression-like behavior." (PMID 35431833, 2022). "TAAR5-KO mice display an antidepressant-like phenotype, decreased anxiety, and increased adult neurogenesis." (PMID 35328548, 2022). "Previous studies revealed that TAAR5-KO mice have a distinct behavioral phenotype, which is characterized by reduced anxiety-like behaviors and better cognitive performance in the decision-making task due to a reduced number of errors, and displayed a greater rate of improvement." (PMID 41511323, 2025). "Additionally, TAAR5-KO mice demonstrate less anxiety- and depressive-like behavior and improved cognitive functions, given the fewer errors in the timing tasks." (PMID 39594659, 2024). "In summary, we have identified seven new TAAR5 antagoniststhat could serve as lead candidates for the development of new treatmentsfor depression, anxiety, and neurodegenerative diseases." (PMID 37847527, 2023). "Given a prominent role of serotonin system in the regulation of anxiety- and depression-related emotional behaviors, these data provide plausible mechanistic explanation for an altered emotional state of TAAR5-KO mice." (PMID 32194374, 2020). "Furthermore, in the elevated plus maze test, TAAR5-KO animals also showed decreased anxiety, an increased number of entrances (p < 0.05), an augmented total time spent in the open arms (p < 0.01), and an increased number of head dippings (p < 0.05)." (PMID 32194374, 2020). "Furthermore, TAAR5-KO animals in the circular open field test showed increased number of the entrances to the central zone (p < 0.01), indicating decreased anxiety in mutant animals." (PMID 32194374, 2020). "Indeed, in our study, we observed significant alterations in various measures of anxiety and affectivity of TAAR5-KO mice in a number of behavioral tests used to test putative anxiolytic and antidepressant drugs." (PMID 32194374, 2020). "Additionally, TAAR5 has also been found to have an effect on anxiety; it is proposed that a TAAR5 antagonist might produce anxiolytic effects." (PMID 40351432, 2025). "In addition, TAAR5 has emerged as a potential regulator of anxiety, suggesting that these trace amine receptors could play key roles in mental health." (PMID 40351432, 2025).
Anxiety (continued). "In addition, in the elevated zero-maze test, another common test used to assess the level of anxiety in mice, TAAR5-KO animals spent more time in the open arms (p < 0.05), but showed similar latency entering into the open arms (92.8 ± 30.60 vs. 91.7 ± 34.14 s; p = 0.98)." (PMID 32194374, 2020). "Moreover, TAAR5 is found in deeper layers projecting to the limbic olfactory circuitry and in various limbic brain regions, such as the amygdala, hippocampus, and hypothalamic nuclei, which are critical areas involved in the stress response and anxiety regulation." (PMID 40351432, 2025). "However, recent studies showed that TAAR5 is also expressed in the limbic brain regions and is involved in the regulation of emotional behaviour and adult neurogenesis, suggesting that TAAR5 antagonism may represent a novel therapeutic strategy for anxiety and depression." (PMID 35328548, 2022). "The absence of TAAR5 did not prevent or reduce stress-induced anxiety in the EPM." (PMID 41511323, 2025). "Moreover, using a series of behavioral tests in mutant mice, we found that the lack of TAAR5 altered emotional behavior, in particular anxiety-and depression-like behavior, and modulated brain serotonin (5-HT) neurotransmission." (PMID 32194374, 2020).
depression (8 papers, 2020 to 2025). "Altered TAAR5 expression is identified in Down syndrome, major depressive disorder, or HIV-associated encephalitis." (PMID 34445502, 2021). "Also, changes in cerebral cortical TAAR5 expression levels were revealed in patients with major depressive disorder or subjects with Down syndrome." (PMID 39594659, 2024). "TAAR5 expression in the prefrontal cortex may be deregulated in etiologically different pathologic conditions such as Down syndrome and major depressive disorder." (PMID 34445502, 2021). "Several studies included in the meta-analysis were devoted to demonstrating the transcriptome dis-balances in schizophrenia, bipolar disorder or major depressive disorder, but only one demonstrated significant downregulation of TAAR5 in the prefrontal cortex in major depressive disorder." (PMID 34445502, 2021). "No TAAR5 expression dysregulation in striatum is revealed in the patients with bipolar disorder (GSE80336, GSE80655), major depressive disorder (GSE80655), schizophrenia (GSE80655), or HIV-associated neurological disorders (GSE35864)." (PMID 34445502, 2021). "Major depressive disorder also did not impact the TAAR5 expression in the amygdala (GSE54564)." (PMID 34445502, 2021).
schizophrenia (3 papers, 2021 to 2025). A major psychotic disorder characterized by abnormalities in the perception or expression of reality. "Previously, the association of TAAR5 gene polymorphisms with cognitive deficit in patients with schizophrenia was described in the literature." (PMID 40867125, 2025). "At the same time, animal studies demonstrated that TAAR5 agonist α-NETA causes significant alterations of the gamma rhythm of brain activity and sensory gating in a manner consistent with schizophrenia-related deficits." (PMID 40867125, 2025). "Using a transcriptomic-based approach to study cerebellar Taar5 expression dysregulation may shed light on their role in the pathogenesis of DA-related mental diseases, including schizophrenia." (PMID 40867125, 2025). "As TAAR1 might become a new target for schizophrenia since the discovery of D2 dopamine receptor blocking the action of antipsychotics more than 50 years ago, TAAR5 may emerge as a novel target for mood disorders." (PMID 35328548, 2022). "No TAAR5 expression disbalance was demonstrated in bipolar disorder or schizophrenia patients in the same dataset." (PMID 34445502, 2021). "TAAR5-KO mice demonstrate anxiolytic/antidepressant-like phenotype; at the same time animals treated with non-selective TAAR5 agonist α-NETA have disrupted synchronization of cortical gamma rhythms and deregulated sensory gating mirroring pathological changes in schizophrenia." (PMID 34445502, 2021).
cognitive deficit (2 papers, 2022 to 2025). "This evidence makes TAAR5 an attractive new target for drug discovery, especially for mood disorders and possibly for cognitive impairment." (PMID 35328548, 2022). "A-NETA, which is known as an inhibitor of acetyl-cholinesterase, shows good activity in activating TAAR5 and has interesting in vivo properties in rodents, such as producing a behaviour consistent with psychosis-related cognitive deficits." (PMID 35328548, 2022).
anxiety disorder (1 paper, 2025). A category of psychiatric disorders which are characterized by anxious feelings or fear often accompanied by physical symptoms associated with anxiety. "Future research should focus on exploring TAAR5 as a promising novel therapeutic target for conditions such as PTSD and anxiety disorders." (PMID 41511323, 2025).
breast carcinoma (1 paper, 2019). "Indeed, higher expression of TAAR1, TAAR2, TAAR4, TAAR5, TAAR8 (in ER- cases) and TAAR9 provided better survival in breast cancer." (PMID 30718646, 2019).
Down syndrome (1 paper, 2021). "TAAR5 downregulation in the prefrontal cortex area also was demonstrated in Down syndrome." (PMID 34445502, 2021).
Dyskinesia (1 paper, 2024). A movement disorder which consists of effects including diminished voluntary movements and the presence of involuntary movements. "Ras-ERK signal transduction cascade, whose components are downregulated in TAAR5-KO mice, is involved in the MSN synaptic plasticity; however, its activation in the striatum may be associated with compulsive behavior, drug addiction, neurodegeneration, or L-DOPA-induced dyskinesia." (PMID 39594659, 2024).
encephalitis (1 paper, 2021). An acute inflammatory process affecting the brain parenchyma. "There is significant up-regulation of TAAR5 in white matter in humans with HIV-associated encephalitis (HIVE), as demonstrated by the microarray hybridization in the GSE35864 dataset." (PMID 34445502, 2021). "The possibility that upregulation of white matter TAAR5 in HIVE patients may be due to encephalitis-related infiltration of B-cells that are known to express TAAR5 should be investigated." (PMID 34445502, 2021).
frontotemporal lobar degeneration (1 paper, 2021). "No significant influence of frontotemporal lobar degeneration on TAAR5 expression in the cerebellum was defined in the GSE13162 dataset." (PMID 34445502, 2021).
melanoma (1 paper, 2022). A malignant, usually aggressive tumor composed of atypical, neoplastic melanocytes. "Essentially undetectable TAAR1, TAAR2, and TAAR5 expression levels were observed in melanoma samples." (PMID 35053262, 2022). "Differential expression analysis demonstrated the drastic decrease of TAAR1, TAAR2, TAAR5, TAAR6, and TAAR8 expression in melanomas compared to benign nevi with only TAAR6, TAAR8, and TAAR9 remaining detectable in malignant tumors." (PMID 35053262, 2022).
mood disorder (1 paper, 2022). A cognitive disorder a disturbance in which the person's mood is hypothesized to be the main underlying feature. "Given the potential application of TAAR5 antagonists in mood disorders, finding novel ligands with new chemical structures and better pharmacodynamics and pharmacokinetic profiles would be a step forward in psychopharmacology." (PMID 35328548, 2022).
multiple sclerosis (1 paper, 2021). A progressive autoimmune disorder affecting the central nervous system resulting in demyelination. "In contrast, in the GSE138614 and GSE123496 datasets, a similar frequency of TAAR5 expression is detected in healthy controls and patients with multiple sclerosis." (PMID 34445502, 2021).
thalassemia (1 paper, 2021). An inherited blood disorder characterized by a decreased synthesis of one of the polypeptide chains that form hemoglobin. "Thalassemia-like erythrocyte abnormalities are characterized by nucleated RBC (nRBC) in blood samples, but no such pathologies were observed in TAAR5-KO mice." (PMID 34298937, 2021).
cancer (3 papers, 2018 to 2023). A tumor composed of atypical neoplastic, often pleomorphic cells that invade other tissues. "Also, it cannot be ruled out that the identified difference in the expression of TAAR2 and TAAR5 mirrors the loss of cancer-promoting pathways in tumor stroma." (PMID 37759760, 2023). "We estimated TAARs’ (including TAAR1, TAAR2, TAAR5, TAAR6, TAAR8, and TAAR9) associations with BC stage, grade, and molecular subtypes in these data and identified that the expression of all TAARs was associated with more unfavorable cancer subtypes, including basal-like and HER2-positive tumors." (PMID 37759760, 2023). "RNAseq data from 12 published cancer studies obtained from cBioPortal detected RNA for TAAR1, TAAR2, TAAR5, TAAR6, TAAR8, and TAAR9 in various cancers." (PMID 29997511, 2018).
psychiatric disorder (2 papers, 2020 to 2025). A disorder characterized by behavioral and/or psychological abnormalities, often accompanied by physical symptoms. "This deletion has also been associated with alterations in monoaminergic transmission within brain regions such as the striatum and hypothalamus, emphasizing the potential impact of TAAR5 in regulating psychiatric disorders." (PMID 40351432, 2025). "Previous studies have indicated that alpha-NETA can induce psychotic-like behavioral abnormalities and affect dopamine transmission in the striatum, revealing that TAAR5 might participate in psychiatric disorders in regulating monoaminergic system." (PMID 40351432, 2025).
brain disorder (1 paper, 2021). A disease affecting the brain or part of the brain. "Thus, TAAR5 can potentially be involved in the pathogenesis of brain disorders and represents a valuable novel target for neuropsychopharmacology." (PMID 34445502, 2021).
neoplasm (1 paper, 2023). A benign or malignant tissue growth resulting from uncontrolled cell proliferation. "Currently, the expression pattern of TAARs in CAFs remains undiscovered, and immune-cell-infiltrating tumors seem to be the most probable source of TAAR mRNA, including TAAR2 and TAAR5 in tumor stroma." (PMID 37759760, 2023). "The identified differences in TAAR2 and TAAR5 expression levels between tumor cells and stroma seem to be reproducible in different groups, including inflammatory cancer, whilst tumorous and stromal cells demonstrate similar expression levels of TAAR1, TAAR6, and TAAR8." (PMID 37759760, 2023). "The overlap between genes co-expressed with TAARs in primary tumors and metastatic lesions is significant, and we found correlations between the expression levels of TAAR1, TAAR2, TAAR5, TAAR8, and TAAR9 and genes associated with neuroactive ligand signaling in both kinds of neoplasms." (PMID 37759760, 2023).
TAAR5 also shares sentences with these, for which no sentence is quoted: Anosmia (2 papers); Parkinson disease (2); Alzheimer disease (1); bipolar disorder (1); cardiomyopathy (1); fibromyalgia (1); Huntington disease (1); neurodegenerative disease (1); neurological disorders (1); renal carcinoma (1); spinal cord injury (1).